IGLV3-32 (immunoglobulin lambda variable 3-32 (non-functional))
Description:
Probable non-functional open reading frame (ORF) of V region of the variable domain of immunoglobulin light chains. Non-functional ORF generally cannot participate in the synthesis of a productive immunoglobulin chain due to altered V- (D)-J or switch recombination and/or splicing site (at mRNA level) and/or conserved amino acid change (protein level). Immunoglobulins, also known as antibodies, are membrane-bound or secreted glycoproteins produced by B lymphocytes. In the recognition phase of humoral immunity, the membrane-bound immunoglobulins serve as receptors which, upon binding of a specific antigen, trigger the clonal expansion and differentiation of B lymphocytes into immunoglobulins-secreting plasma cells. Secreted immunoglobulins mediate the effector phase of humoral immunity, which results in the elimination of bound antigens. The antigen binding site is formed by the variable domain of one heavy chain, together with that of its associated light chain. Thus, each immunoglobulin has two antigen binding sites with remarkable affinity for a particular antigen. The variable domains are assembled by a process called V-(D)-J rearrangement and can then be subjected to somatic hypermutations which, after exposure to antigen and selection, allow affinity maturation for a particular antigen.
Synonyms: IGLV332; V2-23P
Gene: Immunoglobulin variable (V) gene on chromosome 22 (22,594,528 to 22,595,056, forward strand). Ensembl gene ENSG00000211657.
Subcellular location: Secreted; Cell membrane
Gene Ontology:
Biological process: immune response
Cellular component: extracellular region; immunoglobulin complex; plasma membrane
Homologues: Orthologues: tropical clawed frog igl (50% identical). Paralogues in human: IGLV3-19 (70% identical), IGLV3-25 (67% identical), IGLV3-16 (65% identical), IGLV3-21 (65% identical), IGLV3-9 (65% identical), IGLV3-1 (64% identical), IGLV3-10 (63% identical), IGLV3-27 (63% identical), IGLV3-12 (61% identical), IGLV3-22 (61% identical), IGLV1-40 (55% identical), IGLV2-11 (54% identical), and 81 more.